NOS3 (nitric oxide synthase 3)
Description:
Produces nitric oxide (NO) which is implicated in vascular smooth muscle relaxation through a cGMP-mediated signal transduction pathway. NO mediates vascular endothelial growth factor (VEGF)-induced angiogenesis in coronary vessels and promotes blood clotting through the activation of platelets. [Isoform eNOS13C]: Lacks eNOS activity, dominant-negative form that may down-regulate eNOS activity by forming heterodimers with isoform 1.
Synonyms: cNOS; NOSIII; eNOS; ECNOS; EC-NOS; MYMY8
Tractability: Small molecule: a drug acting on it is in phase 2 or 3 trials; a structure with a bound ligand is known; a high-quality ligand is known; it has a high-quality binding pocket; it belongs to a druggable protein family. Antibody: its Gene Ontology location is reachable by antibodies, with high confidence; UniProt places it where antibodies can reach, with medium confidence. PROTAC: ubiquitination databases record sites on it; a small molecule that binds it is known.
Target class: Enzyme
Safety:
Unwanted effects reported when the protein is acted on. In parentheses: how it was acted on, where the effect was seen, and who reports it.
Hypertension (inhibition; source: AOP-Wiki)
in-stent restenosis (source: ClinPGx)
Gene: Protein-coding gene on chromosome 7 (150,991,017 to 151,015,653, forward strand). Ensembl gene ENSG00000164867.
Subcellular location: Cell membrane; Membrane, caveola; Cytoplasm, cytoskeleton; Golgi apparatus
Pathways (Reactome):
Metabolism: NOSIP mediated eNOS trafficking; NOSTRIN mediated eNOS trafficking; Tetrahydrobiopterin (BH4) synthesis, recycling, salvage and regulation; eNOS activation
Signal Transduction: Extra-nuclear estrogen signaling; VEGFR2 mediated vascular permeability
Cellular responses to stimuli: High laminar flow shear stress activates signaling by PIEZO1 and PECAM1:CDH5:KDR in endothelial cells
Hemostasis: Nitric oxide stimulates guanylate cyclase
Immune System: ROS and RNS production in phagocytes
Gene Ontology:
Molecular function: actin monomer binding; arginine binding; calmodulin binding; heme binding; nitric-oxide synthase activity; protein binding; tetrahydrobiopterin binding; cadmium ion binding; flavin adenine dinucleotide binding; FMN binding; NADP binding; superoxide-generating NAD(P)H oxidase activity; oxidoreductase activity; scaffold protein binding
Biological process: endothelial cell migration; L-arginine catabolic process; nitric oxide biosynthetic process; positive regulation of angiogenesis; positive regulation of blood vessel endothelial cell migration; regulation of systemic arterial blood pressure by endothelin; removal of superoxide radicals; response to fluid shear stress; aortic valve morphogenesis; blood vessel diameter maintenance; blood vessel remodeling; cell redox homeostasis; endocardial cushion morphogenesis; homeostasis of number of cells within a tissue; mitochondrion organization; negative regulation of biomineral tissue development; negative regulation of blood pressure; negative regulation of cell population proliferation; negative regulation of extrinsic apoptotic signaling pathway via death domain receptors; negative regulation of muscle hyperplasia; negative regulation of platelet activation; nitric oxide metabolic process; positive regulation of gene expression; positive regulation of Notch signaling pathway; pulmonary valve morphogenesis; and 11 more
Cellular component: caveola; cytoplasm; Golgi apparatus; plasma membrane; cytosol; endocytic vesicle membrane; Golgi membrane; nucleus; cytoskeleton
Genetic constraint (gnomAD): Loss-of-function variants: 98 observed, 128.86 expected, observed/expected ratio (o/e) 0.76, 90% interval 0.64 to 0.9. The upper end of that interval is the gene's LOEUF score, 0.9, which puts it in group 3 of 6, group 1 being the genes least tolerant of losing a copy. Missense variants: 1,443 observed, 1,606.3 expected, observed/expected ratio (o/e) 0.9, 90% interval 0.86 to 0.94. Synonymous variants: 705 observed, 682 expected, observed/expected ratio (o/e) 1.03, 90% interval 0.97 to 1.1.
Homologues: Orthologues: chimpanzee NOS3 (99% identical), macaque NOS3 (99% identical), rabbit NOS3 (96% identical), pig NOS3 (96% identical), guinea pig NOS3 (95% identical), mouse Nos3 (94% identical), rat Nos3 (91% identical), tropical clawed frog nos3 (64% identical). Paralogues in human: NOS1 (57% identical), NOS2 (48% identical), POR (17% identical), MTRR (16% identical), NDOR1 (13% identical).
Diseases named in the same sentence as NOS3 in open-access papers:
NOS3 is named in the same sentence as 393 diseases in open-access papers, as found by Europe PMC text mining. Sharing a sentence is not in itself a finding about the gene and the disease. The quoted sentences say what the papers report.
endothelial dysfunction (387 papers, 2009 to 2026). In vascular diseases, endothelial dysfunction is a systemic pathological state of the endothelium (the inner lining of blood vessels) and can be broadly defined as an imbalance between vasodilating and vasoconstricting substances produced by (or acting on) the endothelium. "Previous studies have reported an association of this polymorphism with endothelial dysfunction due to the decreased NOS3 activity in patients with early-onset primary hypertension, diabetes mellitus, and subarachnoid hemorrhage." (PMID 40142738, 2025). "This study aimed to evaluate the impact of genetic variants on disease outcomes, given that the clinical manifestations of COVID-19 have been linked to endothelial dysfunction and the role of NOS3 in vascular function." (PMID 40142738, 2025). "The alteration of NOS3 activity is accompanied by the reduction in NO bioavailability and endothelial dysfunction, further increasing the cardiovascular risk." (PMID 39796593, 2024). "We found that adipocyte-specific NOS3 knockout mice exhibited exacerbated obesity-induced hypertension associated with endothelial dysfunction and vascular remodelling." (PMID 37897505, 2023). "Endothelial dysfunction has been characterized in HFpEF by a decrease in the production of •NO, leading to a decrease in vasodilation, as a consequence of the NOS3 protein loss of function." (PMID 35633883, 2022). "The genetic factors include allelic variants of the NOS3 gene coding for endothelial nitric oxide synthase (eNOS), which lead to endothelial dysfunction and an increased risk of cardiovascular disorders." (PMID 35886486, 2022). "As one of the key links in the development of AH is endothelial dysfunction, the main pool of associative molecular genetic studies is aimed at finding associations of the development of AH with SNVs in the NOS3 gene." (PMID 34200123, 2021). "A previous study investigated the interaction between the presence of the NOS3 Glu298Asp polymorphism and the phenol content of virgin olive oil on postprandial endothelial dysfunction." (PMID 32722321, 2020). "Vascular effects of oxidative stress resulted from air pollution are mediated by NOS which is reduced in the presence of the NOS3 894 T polymorphisms leading to endothelial dysfunction." (PMID 30071659, 2018). "Leptin-induced miR21 caused sinusoidal endothelial dysfunction primarily by repressing Grhl3, a protein that has a role in phosphorylating NOS3 and increasing NO bioavailability." (PMID 25658689, 2015). "In many studies Glu298Asp polymorphism of NOS3 gene has been associated with three conditions characterized by endothelial dysfunction, hypertension, myocardial infarction, and carotid atherosclerosis." (PMID 24551766, 2012). "G894T (Glu298Asp) polymorphism is located in exon 7 of the NOS3 gene and has been associated with the development of hypertension and endothelial dysfunction in healthy, smokers young adults." (PMID 19650939, 2009). "Decreased NOS3 expression could lead to lower nitric oxide (NO) bioavailability, a hallmark of endothelial dysfunction, while increased PAI-1 could stimulate atherosclerosis and clot stability." (PMID 38396987, 2024). "According to authors, the T allele of 894GT polymorphism in NOS3 gene may be a marker for endothelial dysfunction which is characteristic for CAD." (PMID 37193968, 2023). "Finally, we observed a reduced gene expression of endothelial NO synthase (NOS3), a hallmark of endothelial dysfunction, in HCAECs expressing progerin, as previously observed in murine endothelial cells expressing progerin." (PMID 32408587, 2020). "Loss of endothelial NOS (NOS3) activity is an established contributor to endothelial dysfunction." (PMID 25303561, 2015). "Loss of Cav-1 has been shown to cause aberrant angiogenesis and endothelial dysfunction, which may be due to NOS3 hyperactivation and oxidative stress." (PMID 25158065, 2014).
endothelial dysfunction (continued). "NOS3 itself can be a superoxide source, thereby causing endothelial dysfunction." (PMID 23397596, 2013). "Multiparity is known to produce endothelial dysfunction through reduced nitric oxide bioavailability, thus, it is plausible that multiparity-induced endothelial dysfunction may be exacerbated in homozygotes of the dysfunctional NOS3 variant." (PMID 22025889, 2011). "Because decreased NOS3 expression is related to endothelial dysfunction, we investigated the possible association between the rs2070744, rs 1799983, and rs79467411 single nucleotide polymorphisms (SNPs) in the NOS3 gene and the risk for RLS in Caucasian Spanish people." (PMID 33732155, 2021). "It is possible that neuronal dysfunction in the hypothalamus and/or endothelial dysfunction with reduced nitric oxide synthase-3 activity are responsible for increased adipocyte leptin expression in Lrp8Δexon19 mice." (PMID 40722764, 2025). "Uremic toxins circulating in blood of CKD patients lead to endothelial dysfunction and decrease NOS3 abundance, resulting in reduced nitric oxide bioavailability." (PMID 38389898, 2024). "NOS3, as an enzyme complex, is a key molecule involved in the occurrence of endothelial dysfunction." (PMID 38195507, 2024). "The CT genotype of MGP (rs4236) polymorphism and CT genotype of NOS3 (rs2070744) polymorphism were found to be associated with decreased FMD, indicating endothelial dysfunction, the harbinger of CVD." (PMID 39246453, 2024). "Among the polymorphisms of NOS3, FMD was significantly reduced in the CT genotype of rs2070744 compared to CC and TT genotypes, indicating an endothelial dysfunction and hence risk of CVD (P value = 0.01)." (PMID 39246453, 2024). "CT genotype of MGP (rs4236) and CT genotype of NOS3 (rs2070744) variants were found to be associated with decreased FMD, indicating endothelial dysfunction, the harbinger of CVD." (PMID 39246453, 2024). "We conclude that genetic variants of MGP and NOS3 enhance the risk of CKD and are associated with endothelial dysfunction, which predisposes to CVD." (PMID 39246453, 2024). "Endothelial dysfunction often results in impaired function of endothelial nitric oxide synthase (eNOS; NOS3) and decreased nitric oxide production." (PMID 38532120, 2024). "It has been shown that imbalanced NOS3 synthesis leads to endothelial dysfunction by increased production of reactive oxygen species (ROS)." (PMID 37383439, 2023). "Plasma TNF-α plays a crucial role in both inflammation-mediated redox distress and endothelial dysfunction and regeneration, affecting NOS3 and VEFGA expression." (PMID 35203700, 2022). "In the present work, we tested RIC therapy in well-accepted preclinical settings of decreased NOS3 and comorbidity, reporting a translationally critical finding in stroke models that endothelial dysfunction and comorbidity abolish the benefits of RIC therapy." (PMID 36290774, 2022). "We first tested the efficacy of RIC therapy given at 1 h post-thrombotic stroke in NOS3+/− mice, an animal model of preexisting NOS3 and endothelial dysfunctions." (PMID 36290774, 2022). "Even NOS3 activity or endothelial-dependent vasodilation, the most studies feature of endothelial dysfunction has been evaluated in only 8 of the 14 models." (PMID 35874523, 2022). "This proinflammatory molecule facilitates the phosphorylation of NOS3, reducing the level of nitric oxide (NO), facilitating endothelial dysfunction, and altering the regeneration process." (PMID 35203700, 2022). "Over the last years, ADMA, the endogenous inhibitor of endothelial nitric oxide synthase (NOS3), has emerged as a cardiovascular molecule reflecting endothelial dysfunction and the vascular changes observed in essential HTN." (PMID 35366246, 2021). "In the aorta, decreased ionophore-stimulated ∙NO production was detected post-LPS, which was compatible with impaired NOS-3-dependent nitric oxide production and endothelial dysfunction." (PMID 31249650, 2019).
endothelial dysfunction (continued). "Uncoupled NOS3 is thought to be a prominent source of endothelial ROS in various disorders connected to endothelial dysfunction, such as hypertension." (PMID 29854092, 2018). "This SNP significantly reduces NOS3 promoter transcription activity, inhibiting NO production which ends in endothelial dysfunction." (PMID 29158878, 2017). "In endothelial cells both arginase-I and arginase-II are expressed during inflammatory conditions, which compete with NOS3 for arginine, resulting in an impaired NOS3-derived NO production and endothelial dysfunction." (PMID 25699985, 2015). "Arginase upregulation, as competitor for the substrate arginine, also contributes to endothelial dysfunction, by NOS3 uncoupling resulting in a decreased NO production." (PMID 25699985, 2015). "As for NOS3, inflammatory conditions and the decreased arginine availability result in NOS3 uncoupling, endothelial dysfunction, with an increased superoxide production and disturbed microcirculatory flow as a result." (PMID 25699985, 2015). "Further, we also show that miR21 KO mice are protected from sinusoidal endothelial dysfunction primarily by increased nitric oxide bioavailability through increased NOS3 phosphorylation." (PMID 25658689, 2015). "The arginase-mediated decreased in L-arginine concentrations and the endotoxin-induced downregulation of NOS3 further impair NOS3-derived NO bioavailability in the microvasculature, which results in endothelial dysfunction." (PMID 24465919, 2014). "However, it has been suggested that contribution of CETP to the formation of small dense LDL-C particles and impairment of NO synthesis in the presence of NOS3 G894T variants that are enhanced in hypercholesterolemia might lead to endothelial dysfunction and atherosclerosis." (PMID 23157875, 2012). "Aging promotes endothelial dysfunction, defined as a reduction in bioavailable nitric oxide (NO) produced by the endothelial isoform of nitric oxide synthase (NOS3)." (PMID 23144940, 2012). "Introduction and objectives: Nitric oxide synthase (NOS3) and dimethylarginine dimethylaminohydrolase 2 (DDAH2) polymorphisms are associated with reduced nitric oxide (NO) synthesis and endothelial dysfunction, increasing the risk of cardiovascular disease (CVD)." (PMID 40144407, 2025). "Genetic studies on endothelial dysfunction and inflammation may have pharmacogenomic implications, warranting further research on the potential role of NOS3 in COVID-19 treatment strategies." (PMID 40142738, 2025). "AKT1, TNF-α, VCAM1, ICAM1, and NOS3 might be the key targets of the anti-endothelial dysfunction activity of biochanin A, and the key pathways might be PI3K-Akt and TNF signaling pathways." (PMID 38195507, 2024). "Oxidative stress can lead to the dysregulation of NOS3 and endothelial dysfunction." (PMID 38195507, 2024). "Thus, our data demonstrate that NOS3/endothelial dysfunctions abolish the benefits of RIC therapy, at least in the early phase of thrombotic stroke, with or without IVT." (PMID 36290774, 2022). "The role of NOS3 in endothelial dysfunction has been discussed." (PMID 34447638, 2021). "NOTCH1, CDKN2A, and NOS3 are involved in the regulation of endothelial dysfunction and may be potential therapeutic targets for ED by modulating autophagy." (PMID 34447638, 2021). "Some SNPs of NOS3 gene can affect NOS3 activity, resulting in endothelial dysfunction and might play a vital role in atherosclerotic heart disease formation." (PMID 33737636, 2021). "With regard to the impact of endothelial dysfunction on blood pressure, it has been previously shown that inhibition of endothelial protectors (such as eNOS; also known as Nos3) can lead to hypertension, demonstrating a role for sFlt-1 in blood pressure regulation." (PMID 30683649, 2019). "NOS3 is vasoprotective and low levels of NOS3 are related to endothelial dysfunction." (PMID 31156624, 2019).
endothelial dysfunction (continued). "Conversely, NOS3 over expression by adenoviral gene delivery reduces renal dysfunction, proteinuria and fibrosis in the 5/6th kidney nephrectomy model, and corrects endothelial dysfunction in angiotensin II-induced hypertensive rats." (PMID 24391884, 2013). "Aortas from Nx rats have dramatic endothelial dysfunction along with reduced NOS3 expression." (PMID 24400147, 2013). "As the majority of stroke patients are presented with endothelial dysfunctions and comorbidities, we tested the hypothesis that NOS3 dysfunction and diabetes will abolish the protective effects of RIC therapy in stroke, and the prior inhibition of GSNOR will turn RIC protective." (PMID 36290774, 2022). "Though there are studies which show the mechanism of leptin based on NOS3 uncoupling, we hypothesized that the proinflammatory role of hepatic leptin might be crucial for endothelial dysfunction by up regulating miR21, a microRNA that has a pronounced role in inflammation." (PMID 25658689, 2015). "Consistently, a recent study performed on 60 Indian patients with documented history of CAD reported a significantly higher frequency of rs1799983 (p < 0.05) compared to control subjects, indicating that variations in NOS3 gene may be useful clinical markers of endothelial dysfunction in CAD." (PMID 24068186, 2013). "Prolonged interferon exposure suppresses endothelial nitric oxide synthase (NOS3) expression and nitric oxide (NO) production, leading to endothelial dysfunction and promoting the progression of atherosclerosis." (PMID 41359111, 2025). "Oxidative stress may lead to endothelial dysfunction, which could result in increased mean arterial pressure, and NO may play a role in this mechanism, but interactions with other vasoactive /biological substances cannot be overlooked, as the gene expressions of NOS3 and NOS2 have been reduced." (PMID 35100630, 2022). "Then, NOTCH1, PPARG, NOS3, KEAP1, CDKN2A, and IRS1 were predicted to affect endothelial dysfunction of ED as autophagy-related hub genes." (PMID 34447638, 2021). "NOS3 dysfunction and oxidative stress that ensues following chronic GTN exposure are likely to accentuate endothelial dysfunction (leading to (cross) tolerance)." (PMID 25158065, 2014). "Biochanin A possibly prevents endothelial dysfunction via a complex network structure with multiple targets and pathways, among which AKT1, TNF-α, NOS3, ICAM-1, and VCAM-1 may be the key targets, according to network pharmacological analysis results." (PMID 38195507, 2024). "Also, in our study, we found that the CT genotype of rs2070744 (NOS3) had decreased FMD, indicating endothelial dysfunction." (PMID 39246453, 2024). "Interestingly, selenium enhanced NOS3 expression similarly to only zinc administration at the early phase of CCAO, thus recovering the endothelial function as shown in an endothelial dysfunction model." (PMID 30258527, 2018). "The fact that genistein (a strong potentiator of NO production via NOS3 activation) did not enhance vasorelaxation in ED+ subjects suggests that impaired NOS3 activity does not have a role in endothelial dysfunction in that context." (PMID 25889611, 2015). "Whether or not empagliflozin improves cardiac function by targeting endothelial dysfunction is possible since it was shown to promote NOS3 phosphorylation, EC survival and quiescence." (PMID 35874523, 2022).